DICER1 (dicer 1, ribonuclease III)
Diseases named in the same sentence as DICER1 in open-access papers (continued):
Sharing a sentence is not in itself a finding about the gene and the disease.
myeloma (3 papers, 2018 to 2022). "In our results, in addition to the classic features of cell senescence, Dicer1-KD MSCs exhibited a significant increase in their capacity to support myeloma cells." (PMID 29724992, 2018). "Besides, co-culture of myeloma cells from patients or myeloma cell lines with MSCs decreased the expression of Dicer1 and that of miR-93/miR-20a in the latter, which was associated with elevated expression of the cell cycle inhibitor p21." (PMID 34067236, 2021). "We confirmed that MM-MSCs and Dicer1-KD MSCs increased the proportions of S phase myeloma cells." (PMID 29724992, 2018). "We observed that myeloma cells could significantly decrease the expression of Dicer1, p21, miR-93 and miR-20a in HC-MSCs." (PMID 29724992, 2018). "The results of the Edu assay showed that Dicer1-KD MSCs and MM-MSC promoted myeloma cell proliferation, and that the proportion of S phase cells was increased compared with that in the HC-MSC or MSC-Negative groups." (PMID 29724992, 2018).
ovarian sarcoma (3 papers, 2015 to 2025). A rare, aggressive malignant mesenchymal neoplasm that arises from the ovary. "To date, five gynandroblastomas, fourteen cervical ERMS and three ovarian sarcomas have been reported in individuals with germline pathogenic DICER1 variants." (PMID 34170462, 2021). "A patient with sarcoma of the ovary had received whole abdomen radiotherapy (WART) and was found to have a germline DICER1 mutation." (PMID 39860595, 2025).
Parkinson disease (3 papers, 2012 to 2023). A progressive degenerative disorder of the central nervous system characterized by loss of dopamine producing neurons in the substantia nigra and the presence of Lewy bodies in the substantia nigra and locus coeruleus. "Altered DICER1 and miRNA regulation have been shown to be involved in other neurodegenerative diseases such as Huntington's and Parkinson's diseases; however, the Alu RNA profiling has not been reported yet." (PMID 24278713, 2012).
rectal cancer (3 papers, 2015 to 2019). A primary or metastatic malignant neoplasm that affects the rectum. "However, when stratified by anatomical sites, DICER1 rs3742330 was significantly associated with rectal cancer." (PMID 30833603, 2019). "Conversely, DICER1 rs3742330 AG heterozygotes had a significantly increased risk of colon but not rectal cancer (AOR = 1.506; 95% CI, 1.020–2.223; P = 0.040)." (PMID 26147304, 2015). "In TCGA, we observed germline DICER1 LOF, splice and hotspot variation in individuals with uterine and rectal cancers, which are not known to be germline DICER1‐associated." (PMID 30672147, 2019).
Renal cyst (3 papers, 2018 to 2023). A fluid filled sac in the kidney. "Conversely, HoxB7-Cre-mediated removal of Dicer1 caused the development of renal cysts in this model Independent studies have also shown the effects of Dicer1 deletion in Foxd1+ progenitor cells, which give rise to renal stroma." (PMID 30459215, 2018). "Based on this consensus, any major criterion, two minor criteria (such as cystic lung disease in adulthood and renal cysts), or a first-degree relative with positive-germline DICER1 should be tested." (PMID 36902703, 2023).
rheumatoid arthritis (3 papers, 2018 to 2025). A chronic, systemic autoimmune disorder characterized by inflammation in the synovial membranes and articular surfaces. "In rheumatoid arthritis, DICER1 expression is reduced in fibroblast-like synoviocytes, which is associated with increased inflammation and cellular senescence." (PMID 40666073, 2025).
soft tissue sarcoma (3 papers, 2021 to 2025). A malignant neoplasm arising from muscle tissue, adipose tissue, blood vessels, fibrous tissue, or other supportive tissues excluding the bones. "Instead, standard regimens used for other cancers, such as rhabdomyosarcoma, germ cell tumor, or soft tissue sarcoma, are most often the treatment paradigms chosen for specific DICER1-associated cancers." (PMID 40634537, 2025).
spindle cell sarcoma (3 papers, 2022 to 2025). A malignant mesenchymal neoplasm composed of spindle-shaped cells. "In summary, a diagnosis of primary intracranial spindle cell sarcoma with neurogenic and myogenic differentiation, possibly associated with DICER1 mutation, was favoured." (PMID 36153506, 2022).
teratoma (3 papers, 2020 to 2023). A non-seminomatous germ cell tumor characterized by the presence of various tissues which correspond to the different germinal layers (endoderm, mesoderm, and ectoderm). "More importantly to the best of our knowledge, the presence of ERMS in an infantile presacral teratoma should alert to the possibility that the tumor may represent a DICER1-associated neoplasm." (PMID 34599283, 2022). "The authors discussed the probability these teratoma-like lesions being a novel DICER1-related entity." (PMID 32507920, 2020). "Yet another primitive multipatterned neoplasm of the thyroid with DICER1 alterations has been reported, apparently distinct from a teratoma, as a “malignant teratoid tumor” or “thyroblastoma” which is likely the same tumor type that Rooper and associates described." (PMID 34599283, 2022).
yolk sac tumor (3 papers, 2020 to 2023). A non-seminomatous malignant germ cell tumor composed of primitive germ cells. "However, immature cartilage in association with spindle cells and rhabdomyoblasts should in the absence of other teratomatous elements and/or yolk sac tumor raise the possibility of DICER1-associated presacral malignant teratoid neoplasm." (PMID 34599283, 2022).
adrenocortical carcinoma (2 papers, 2015 to 2022). "But, among adrenocortical carcinomas, a weak DICER1 expression was significantly more frequent in metastatic than in non-metastatic adrenocortical carcinomas (66% vs. 31%; p = 0.002)." (PMID 26087193, 2015).
Atrophy (2 papers, 2016 to 2024). Any weakening or degeneration, especially through lack of use. "Alu RNA accumulation and DICER1 deficit stimulates retinal pigmented epithelium degeneration and geography atrophy in age-related macular degeneration." (PMID 27653551, 2016).
bipolar disorder (2 papers, 2015 to 2016). A disorder of the brain that causes unusual shifts in mood, energy, activity levels and the ability to carry out day-to-day tasks. "We found that DICER1 mRNA level was significantly reduced in the cases relative to the controls after we adjusted simultaneously for sex, age, population substructure, current alcohol and drug use disorders, current psychotic disorder, bipolar disorder and estimated blood cell counts." (PMID 26632874, 2015).
bladder (2 papers, 2018 to 2022). "We recently have described one giant botryoid fibroepithelial polyp of the urinary bladder, which showed two non-synonymous DICER1 pathogenic variants." (PMID 34282560, 2022). "Finally, Dicer-1 ribonuclease type-III (DICER1) is involved in mi-RNA production and its inhibition triggers resistance of tubular cells in a mouse model of kidney IRI63." (PMID 29654283, 2018).
breast tumors (2 papers, 2011 to 2015). "We found that these genes were deregulated in ER+ compared to ER− breast tumors: DICER1, DROSHA and DGCR8 were significantly under-expressed in ER− while AGO2 was moderate over-expressed in ER−." (PMID 26141719, 2015).
clear cell renal cell carcinoma (2 papers, 2021 to 2023). "miR-122 exerted its prometastatic properties in clear-cell renal cell carcinoma cells by downregulating DICER1 and its downstream effector, the miR-200 family, thereby inducing EMT." (PMID 37495108, 2023).
Cowden syndrome (2 papers, 2022 to 2023). "One patient was diagnosed with Gardener syndrome and columnar subtype of PTC, two with DICER1 and thyroid follicular nodular disease, and one with Cowden syndrome and oncocytic carcinoma." (PMID 37274328, 2023).
endometrial adenocarcinoma (2 papers, 2022 to 2024). "Endometrial adenocarcinoma samples exhibited an increased number of hotspot biallelic DICER1 mutations, based on the TCGA PanCancer and MSK-IMPACT (Memorial Sloan Kettering Integrated Mutation Profiling and Actionable Cancer Targets) databases." (PMID 38836981, 2024). "DICER1 is thought to have a substantial role in endometrial adenocarcinoma even though loss of PTEN is a feature of this cancer." (PMID 38836981, 2024). "Dicer1 and PTEN-deficient mice developed endometrial adenocarcinomas that were poorly differentiated and overexpressed the clear-cell adenocarcinoma markers, HNF1B (hepatocyte nuclear factor 1 homeobox B), and napsin A. These adenocarcinomas did not respond to hormones." (PMID 38836981, 2024).
Familial adenomatous polyposis (2 papers, 2022). Familial adenomatous polyposis (FAP) is characterized by the development of hundreds to thousands of adenomas in the rectum and colon during the second decade of life. "The syndromic ones include familial adenomatous polyposis (FAP), Cowden syndrome, Werner syndrome, Carney complex, DICER1-pleuropulmonary blastoma familial tumor predisposition syndrome and Pendred syndrome." (PMID 36553142, 2022).
germ cell neoplasms (2 papers, 2020 to 2023). "In this context, it is worth mentioning that DICER1 mutations are very uncommon in germ cell neoplasms." (PMID 32507920, 2020). "Taken together, these very recent studies highlight the existence of two distinctive categories of aggressive malignant teratoid tumors unrelated to genuine germ cell neoplasms: one driven by SMARCA4 inactivation and another related to DICER1 mutations." (PMID 32507920, 2020).
glaucoma (2 papers, 2022 to 2023). Increased pressure in the eyeball due to obstruction of the outflow of aqueous humor. "Genotype association analysis of rs3742330 variant in DICER1 with primary open-angle glaucoma and primary angle-closure glaucoma." (PMID 37099569, 2023). "The underlying potential mechanism(s) linking DROSHA and DICER1 polymorphisms (rs10719 and rs3742330) to glaucoma pathogenesis is unknown." (PMID 37099569, 2023). "Although studies have reported the genetic association of miRNA biogenesis gene polymorphisms, DICER1 (rs3642330) and DROSHA (rs10719), in a wide variety of human diseases, however, their genetic contribution in glaucoma has not been much investigated." (PMID 37099569, 2023). "In addition, both the polymorphisms rs3742330 (DICER1) and rs10719 (DROSHA) showed no significant genotype influence on glaucoma-specific clinical indices such as IOP, cup/disk ratio, and the number of antiglaucoma medications." (PMID 37099569, 2023).
glomerulosclerosis (2 papers, 2018 to 2023). A hardening of the kidney glomerulus caused by scarring of the blood vessels. "Similarly, conditional deletion of Dicer1 in mature podocytes resulted in glomerular abnormalities, such as glomerulosclerosis and fibrosis, and podocyte-specific deletion of Drosha resulted in collapsing glomerulopathy comparable to the phenotype of Dicer1 knockouts." (PMID 30459215, 2018).
GLOW syndrome (2 papers, 2022 to 2023). "The phenotypic overlap between patients with p.S1344L mutation and GLOW syndrome provide clinical support for recent discoveries that RNase IIIa-Ser1344 site mutations impede miRNA-5p biogenesis analogous to DICER1 hotspot mutations in the RNase IIIb domain." (PMID 33208384, 2022).
head and neck cancer (2 papers, 2019 to 2023). A primary or metastatic malignant neoplasm affecting the head and neck. "DICER1*rs1057035 is associated with high risk in CLL (OR = 1.85) and decreased cancer risk in CRC (OR = 0.62), HCC (OR = 0.78), and head and neck cancers (OR = 0.81)." (PMID 36672288, 2023).
Huntington disease (2 papers, 2017 to 2025). Huntington disease (HD) is a rare neurodegenerative disorder of the central nervous system characterized by unwanted choreatic movements, behavioral and psychiatric disturbances and dementia. "Based on the YAC128 model of Huntington’s disease, the reduction of Dicer1 expression in vivo leads to a significantly altered composition of the global miRNA pool in the brain." (PMID 39965642, 2025).
Hypertension (2 papers, 2015 to 2019). The presence of chronic increased pressure in the systemic arterial system. "Additionally, our results also demonstrate two feasible interactions, DICER1 rs13078, BMI and TG in T2DM and RAN rs14035, hypertension and duration of T2DM in diabetic macrovascular complications." (PMID 31354628, 2019).
hypothyroidism (2 papers, 2016 to 2021). Abnormally low levels of thyroid hormone. "Disrupting Dicer1 function specifically in thyrocytes has shown downregulation of thyrocyte cell adhesion proteins and cell differentiation, which led to severe hypothyroidism and shortened life span." (PMID 27602775, 2016).
macular degeneration (2 papers, 2016 to 2020). Loss of vision in the central portion of the retina (macula), secondary to retinal degeneration. "More recently, DICER1 decline in aging retina has been linked to Alu retrotranspon activation and macular degeneration." (PMID 27072046, 2016). "In macular degeneration, elevated levels of Alu RNA and inflammasome activation result from reduced levels of the enzyme DICER1, one of whose metabolic functions is to catabolize Alu RNAs20,23,24." (PMID 32968070, 2020). "Elevated levels of Alu RNA and inflammasome activation in macular degeneration result from reduced levels of the enzyme DICER1, one of whose metabolic functions is to catabolize Alu RNAs20,23,24." (PMID 32968070, 2020).
medulloblastoma (2 papers, 2015 to 2025). A malignant, invasive embryonal neoplasm arising from the cerebellum. "In humans, germline (including DICER1 syndrome) and somatic mutations of one copy of DICER1 has been described in different tumor types, including one human medulloblastoma." (PMID 26091048, 2015). "Our results are in accordance with previous studies reporting the accumulation of DNA damage in mouse epidermis, cerebellum and medulloblastoma following Dicer1 total deletion." (PMID 41002430, 2025).
Microprolactinoma (2 papers, 2018 to 2020). A pituitary prolactin cell adenoma of less than 10 mm diameter. "DICER1 carriage and microprolactinoma are both rare, but here are reported in the same individual, suggesting association." (PMID 30306785, 2018).
nodular goiter (2 papers, 2020 to 2023). Goiter characterized by discrete tissue mass(es) that may or may not produce thyroid hormones. "Likewise, the elder sister in this report had a nodular goiter in the past, and both patients, their father, and grandmother carried DICER1 mutations." (PMID 32629665, 2020).
oncocytic tumors (2 papers, 2025). "We propose an algorithm for identifying DICER1-related thyroid lesions, with a focus on oncocytic tumours, to aid clinicians and pathologists in recognising these entities." (PMID 41104964, 2025).
pituitary carcinoma (2 papers, 2017 to 2023). A primary or metastatic malignant neoplasm affecting the pituitary gland. "Pituitary carcinomas rarely occur in genetic syndromes; examples of pituitary carcinoma patients with MEN1 mutations have been documented, whilst AIP, PRKAR1A, DICER1 and GPR101 mutations have not been associated with metastatic spread to date." (PMID 28284009, 2017).
pseudoexfoliation glaucoma (2 papers, 2022 to 2023). "We have previously reported an association of rs3742330 in DICER1 in pseudoexfoliation glaucoma." (PMID 37099569, 2023). "We investigated the association between DICER1 (rs3742330) and DROSHA (rs10719) polymorphisms and pseudoexfoliation glaucoma (PXG) and related clinical phenotypes in a Saudi cohort." (PMID 35328042, 2022).
psychosis (2 papers, 2015 to 2020). "In the whole blood of individuals with first episode psychosis (FEP), DICER1 overexpression may depend on the treatment status and IL-6 peripheral levels." (PMID 33149139, 2020).
PTEN hamartoma tumor syndrome (2 papers, 2022). An autosomal dominant syndrome caused by pathogenic variants in the PTEN gene, characterized by hamartomas, overgrowth, neurodevelopmental disorders and an increased risk of various cancers, including breast, thyroid, and endometrial cancer. "Indeed, it is likely that DICER1 is the main or only genetic cause of pure MNG in childhood, so it is difficult to compare DICER1 to other extremely rare syndromes, such as PTEN hamartoma tumor syndrome." (PMID 36151231, 2022).
retinitis pigmentosa (2 papers, 2020). Retinitis pigmentosa (RP) is an inherited retinal dystrophy leading to progressive loss of the photoreceptors and retinal pigment epithelium and resulting in blindness usually after several decades. "We previously reported that deletion of Dicer1 specifically in MG (Dicer-cKO) causes a rod photoreceptor degeneration and retinal disorganization that resembles end stage retinitis pigmentosa." (PMID 33614628, 2020).
Schwachman-Diamond syndrome (2 papers, 2020 to 2022). "The loss of Dicer1 is associated with reduced expression of the ribosome maturation factor encoded by the SBDS (Shwachman-Bodian-Diamond syndrome) gene mutated in Schwachman-Diamond syndrome, a human congenital BM failure with known leukemia predisposition." (PMID 32443460, 2020).
seminoma (2 papers, 2013 to 2021). A radiosensitive malignant germ cell tumor found in the testis (especially undescended), and extragonadal sites (anterior mediastinum and pineal gland). "Another study did not identify a DICER1 mutation in a man with a seminoma, who was the relative of a patient with a PPB." (PMID 23547758, 2013).
sex cord-stromal tumor (2 papers, 2025). A neoplasm involving a sex cord. "Therefore, we share the management experience of this rare mixed sex-cord-stromal tumor case, as it is associated with clinical recurrence and DICER1 mutation, providing some diagnostic insights for clinicians." (PMID 40901169, 2025). "This case involves a recurrent mixed sex-cord-stromal tumor associated with juvenile GCT and DICER1 gene mutation, warranting further research and discussion." (PMID 40901169, 2025).
synovial sarcoma (2 papers, 2012 to 2025). "The morphologic presentation of a sarcomatous, monomorphic spindle cell proliferation raised a broad differential diagnosis including malignant peripheral nerve sheath tumor (MPNST), primary intracranial sarcoma, DICER1‐mutant, and synovial sarcoma (SS)." (PMID 40159593, 2025). "Furthermore, miR-144, identified as switching specifically in non-myxoid liposarcoma, and synovial sarcoma, is predicted to target DICER1." (PMID 22823907, 2012).
T-cell lymphoma (2 papers, 2015 to 2019). "However, the regulation of these miRNAs of DICER1 rs3742330 in CRC and T-cell lymphoma has not been experimentally validated." (PMID 26147304, 2015).
Adult onset (1 paper, 2024). Onset of disease manifestations in adulthood, defined here as at the age of 16 years or later. "Somatic mutations in DICER1 RNase IIIb hotspots have been shown in a wide variety of RAS-like lesions, ranging from benign FTA, NIFTP, to malignant FTC and FVPTCs, highlighting an association to early- and adult-onset thyroid lesions with a favorable prognosis." (PMID 38252873, 2024).
adult T cell Leukemia (1 paper, 2023). "Interestingly, the authors measured DROSHA, DGCR8, XPO5, DICER1, AGO2, and AGO3 mRNA expression, and only DICER1 mRNA was differently expressed in CD8+ T-cell–depleted PBMCs from HTLV-1 asymptomatic carriers when compared to patients with acute adult T cell Leukemia." (PMID 37243263, 2023).
allergic asthma (1 paper, 2020). A asthma with a basis in a pathological type I hypersensitivity reaction. "In the other pair of 19-month-old female babies, one had a history of bronchopulmonary hypoplasia and developed PPB(III) without DICER1 mutation, and her identical sibling had allergic asthma." (PMID 33028416, 2020).
anaplastic carcinomas (1 paper, 2025). "DICER1 mutations have also been reported in a few high-grade non-anaplastic carcinomas – including poorly differentiated thyroid carcinoma – and in rare anaplastic carcinomas." (PMID 41175860, 2025).